GABARAP (GABA type A receptor-associated protein)
Diseases named in the same sentence as GABARAP in open-access papers (continued):
Sharing a sentence is not in itself a finding about the gene and the disease.
Tourette syndrome (1 paper, 2024). A neurologic disorder caused by defective metabolism of the neurotransmitters in the brain. "In humans, trafficking of the GABA(A) receptor by GABARAP can lead to obsessive behaviors and learning deficits often in seen in neurological disorders such as Tourette’s Syndrome." (PMID 38882929, 2024).
tumor (26 papers, 2010 to 2025). "To explain the role and potential mechanism of GABARAP in regulating tumor development, we performed acquisition and loss of function experiments using cell lines and models of mouse xenotransplantation." (PMID 33591943, 2021). "Few studies have focused on γ-aminobutyric acid type A (GABAA) receptor-associated protein (GABARAP) in tumor progression." (PMID 33591943, 2021). "Carcinogen-induced tumor incidence was significantly reduced in GABARAP-deficient mice." (PMID 36430876, 2022). "In this model, GABARAP KO was associated with reduced tumor incidence." (PMID 27933272, 2016). "Additionally, an Atg8/LC3 family member implicated in autophagy and tumor suppression was associated with alterations to cell death and cytokine secretion in mice lacking gamma-aminobutyric acid receptor-associated protein (GABARAP)." (PMID 31277291, 2019). "Subsequent scRNA-seq analysis of malignant subpopulations (Ost_1 and Cho_2) revealed three key genes (GABARAP, BNIP3, EIF2AK3) consistently overexpressed in tumor cells and linked to poor outcomes." (PMID 41346635, 2025). "We also discussed the possible role of GABARAP in tumor progression through the regulation of autophagy." (PMID 40900801, 2025). "This illustrates the intricate functional role of GABARAP in tumor development and highlights the complexity of the mechanisms underlying cancer initiation and progression." (PMID 39664581, 2024). "Further investigations are needed to demonstrate the antitumor effect of tumor-antigens fused with GABARAP and GABARAPL1." (PMID 36139357, 2022). "The results demonstrated that the expression of GABARAP gradually declined with the increase of tumor malignancy." (PMID 33591943, 2021). "GABARAP negatively correlated with advanced clinicopathological features in clinical specimens, such as tumor size and TNM stage." (PMID 33591943, 2021). "Previous studies also reported the role of GABARAP in tumor autophagy, drug resistance and apoptosis." (PMID 33591943, 2021). "We constructed an orthotopic tumor model in nude mice in vivo, and the experimental results showed that GABARAP inhibited the growth of tumors in vivo, which is consistent with the relevant results." (PMID 33591943, 2021). "Low levels of GABARAP increased p-AKT and p-mTOR levels, and a specific AKT pathway inhibitor reversed the downregulation of GABARAP-induced tumor progression." (PMID 33591943, 2021). "In order to investigate the potential roles of GABARAP in tumor incidence, female GABARAP KO (KO) and wild-type C57BL/6J (Wt) mice were treated with DMBA." (PMID 27124579, 2016). "In this study, we examined the potential role of GABARAP in tumor formation induced by the chemical carcinogen DMBA." (PMID 27124579, 2016). "Besides, we found that GABARAP expression exhibited widespread tumor distribution with pronounced enrichment in malignant Ost/Cho cells." (PMID 41346635, 2025). "In addition, there exists an inverse correlation between GABARAP expression and advanced clinicopathological characteristics (e.g., tumor size and tumor node metastasis (TNM) stage) in clinical samples." (PMID 39664581, 2024). "The silencing of GABARAP significantly increased the tumor volumes and weights compared to control." (PMID 33591943, 2021). "In KRAS-mediated lung tumors, the depletion of Atg5 or Atg7, two mitophagic effectors involved in LC3/GABARAP lipidation, has induced a reduction in tumor burden and an increase in survival compared to the counterpart even if malignancies present a faster tumor-initiation stage." (PMID 31210843, 2019). "FLCN has been shown to bind FNIP1, FNIP2, the Rag GTPases A and C/D, GABARAP and plakophilin-4 (refs 11, 12, 13, 14, 15, 16, 17, 18), but the biological significance of each of these interactions with regards to the tumour suppressor function of FLCN is under investigation." (PMID 28656962, 2017).
tumor (continued). "In summary, we have identified a novel role of GABARAP in tumorigenesis by using a mouse model and show that ablation of GABARAP in vivo inhibits tumor initiation and progression through enhancement of both antitumor immunity and cell death signaling, as summarized in a working model." (PMID 27124579, 2016). "We demonstrated that the ablation of GABARAP expression significantly diminished tumor incidence." (PMID 27124579, 2016). "The aim of our study was to use a GABARAP KO mouse model to evaluate the potential in vivo role of the gene in tumorigenesis and to clarify whether it acts as a tumor suppressor or enhancer." (PMID 27124579, 2016). "However, the reduced tumor growth observed in PDXs from CRC upon p38 MAPK inhibition with PH797804 did not correlate with consistent changes in the expression of HER-3 or GABARAP mRNAs." (PMID 25890501, 2015). "Some publications have suggested that GABARAPL1 and GABARAP might also be involved in tumour development." (PMID 20197771, 2010). "However, GABARAP has been suggested as a tumor promoter and suppressor." (PMID 36430876, 2022). "However, LY-294002 reversed GABARAP-mediated inhibition of tumor formation." (PMID 33591943, 2021). "Studies have shown a decrease in the expression of GABARAP and GABARAPL1 in different types of tumor tissues." (PMID 39664581, 2024). "The results showed that both GABARAP and GABBR2 were highly expressed in the tumor tissues, and the fold change of GABBR2 was more significant." (PMID 38105184, 2023). "In this work, we investigated the potential role of GABARAP and GABARAPL1, two members of the autophagic ATG8 family proteins, as surrogate tumor antigen delivery vectors to prime antitumor T cells." (PMID 36139357, 2022). "In contrast, in the syngeneic tumor cell engraftment system, elevated cytokine expression of IL-1β, IL-6, IL-2 and IFN-γ in GABARAP KO immune cells probably inhibited tumor cell growth." (PMID 34502326, 2021). "Our results show that, in different tumour cell lines, micromolar doses of metformin prevent cell growth by reducing glutamate, ammonia accumulation, autophagy markers such as MAP1LC3B-II and GABARAP as well as degradation of long-lived proteins." (PMID 30646605, 2019). "An inverse correlation (r = −0.57) was also observed between GABARAPL1 mRNA and tumor stage while a very poor correlation was determined between GABARAP or GABARAPL2 expression levels and the tumor grade (respectively r = −0.3 and r = −0.1)." (PMID 26474850, 2015). "The tumor tissues derived from basal, Her2, LumA, and LumB breast tissues were not significantly different between normal and tumor ones; for GABARAP the expression levels are displayed in the box plot." (PMID 34572798, 2021). "Therefore, our goal was to study the regulation of ATG8 family members (GABARAP, GABARAPL1, LC3B) by the NMD and to identify molecular links between these two cellular processes that are involved in tumor development and metastasis formation." (PMID 34680418, 2021). "Few reports focused on GABARAP and EMT-related tumor metastasis." (PMID 33591943, 2021). "In this study, following our identification of the core autophagy regulator Atg8a/GABARAP, Atg7 and Atg9 in a large-scale screen for RasV12-cooperating tumour suppressors in Drosophila, we investigate the tumour-suppressive role of autophagy in Ras-activated tissues." (PMID 28581519, 2017). "Unlike our previous in vitro data, we find that GABARAP acts as tumor enhancer in vivo, which seems to be related to the inhibition of apoptosis and antitumor immune response." (PMID 27124579, 2016). "Moreover, autophagy and autophagy proteins such as p62, GABARAP or GABARAPL1 are conserved, suggesting that our study could be transposed to human vaccinations when tumor-derived antigens are used." (PMID 36139357, 2022). "While GABARAP and GABARAPL2 expression are also reduced in the tumor samples, this decrease was not significant." (PMID 26474850, 2015).
tumor (continued). "To understand the mechanism of this differential effect, we found that ferroptosis inducers upregulate mRNAs encoding multiple direct and indirect autophagy stimulators, such as ATG16L2, ATG9A, ATG4D, GABARAP, SQSTM/p62, SEC23A and BAX, in tumor cells growing in 2D but not in 3D culture." (PMID 37658069, 2023).
cancer (17 papers, 2015 to 2025). A tumor composed of atypical neoplastic, often pleomorphic cells that invade other tissues. "GABARAP is described as being down-regulated in cancer, and high expression is associated with a good prognosis." (PMID 32477008, 2020). "Because CSCs are more dependent on autophagy than normal stem cells, NEAT1v1-induced autophagy via GABARAP might be a possible mechanism underlying the maintenance of cancer stemness." (PMID 35054896, 2022). "This study is the first report demonstrating the involvement of GABARAP-induced mitophagy in the radioresistance of cancer cells." (PMID 36430876, 2022). "The final results indicated that GABARAP was related to the clinicopathological characteristics of malignant tumors." (PMID 33591943, 2021). "In order to characterize the regulation of GABARAP gene family expression in cancer cells, we analyzed their expression and the epigenetic modifications in the promoters of these genes in in vitro human BC cell models." (PMID 26474850, 2015). "ATG5, GABARAP, ATG7, and ULK2 had a higher frequency of loss mutations in the pan-cancer analysis." (PMID 34636718, 2021). "This conclusion is consistent with publicly available data, which suggest that GABARAP may be used as a prognostic predictor of this type of cancer." (PMID 33591943, 2021). "Interestingly, the levels of GABARAP were significantly higher when compared to Xaf1 in normal and malignant breast tissues as well as cancer cell lines from various organs." (PMID 27124579, 2016). "The GABARAP gene has been described to be highly expressed in endocrine tissues while the GABARAPL1 gene is predominantly expressed in the central nervous system but they both are underexpressed in a large variety of cancer cell lines." (PMID 26474850, 2015). "Finally, GABA type A receptor–associated protein like 1 gene (GABARAPL1), coding for GABARAP structural protein of the autophagosome, was the only shared target gene between PI3Kα signature, PI3Kβ signature, compressive stress signature, and “PI3K-AKT REACTOME signaling pathway in cancer” signature." (PMID 39746759, 2025). "In cancer, modulating LC3/GABARAP lipidation sheds light on how autophagy aids tumor cell survival under stress conditions, such as nutrient scarcity or chemotherapy." (PMID 39936034, 2025). "In cancer tissue, only the GABARAPL1 mRNA level was shown to be significantly reduced, whereas those of GABARAP and GABARAPL2 were not." (PMID 30374741, 2018). "Moreover, neither GABARAP nor HER-3 mRNAs were consistently upregulated upon p38 MAPK inhibition in the PDXs and our studies with cancer cell lines suggest that long-term incubation with DMSO or high cell confluency may induce HER-3 and GABARAP independently of p38 MAPK signaling." (PMID 25890501, 2015).
infection (14 papers, 2012 to 2025). The state of being infected such as from the introduction of a foreign agent such as serum, vaccine, antigenic substance or organism. "Our present study further showed that the Cq-GABARAP was also positively associated with WSSV infection for its altered expression and distribution post viral challenge." (PMID 27385304, 2016). "Even under conditions that promoted viral entry, rCq-GABARAP significantly reduced viral replication at an early stage of infection, which was probably caused by the formation of WSSV aggregates in the cytoplasm." (PMID 27385304, 2016). "Namely, the mammalian ATG8 ortholog GABARAP colocalized with UL148 during infection, and both GABARAP and another ATG8 ortholog, LC3B, colocalized with UL148 at the ER structures during ectopic expression of UL148." (PMID 31822584, 2019). "The reduction in Atg3 abundance driven by the infection correlated with an impairment of the lipidated form of LC3 (LC3-II) and GABARAP, particularly at 32 hours post-infection." (PMID 29300789, 2018). "Using qRT-PCR, the transcription of the viral genes was significantly suppressed at 6 hpi after infection with the WSSV pre-incubated with rCq-GABARAP for 0.5 h." (PMID 27385304, 2016). "We next scored the infectious titers of viral particles produced by cells depleted for each LC3/GABARAP protein by infection of HeLa P4R5 indicator cells and normalized them to the amount of CAp24 present in the cell supernatants (referred herein as HIV-1 infectivity)." (PMID 41174262, 2025). "LC3 and GABARAP lipidation also contribute to TFEB activation in response to kidney injury and pathogen infection." (PMID 40195022, 2025). "Upon infection of HeLa cells all members of the LC3- and GABARAP-subfamilies colocalized with about 20% of S. Typhimurium, a number typical for the cytosol-exposed fraction of intracellular S. Typhimurium." (PMID 23022382, 2012). "The number of WSSV virions in the aggregates was probably increased during the WSSV infection process as shown by TEM, implying that Cq-GABARAP might gradually “gather” individual virions or small viral inclusions to form larger viral aggregates intracellularly." (PMID 27385304, 2016). "In addition, the transcript levels of VP28 were similar between the Hpt cell infected with rCq-GABARAP-incubated virus and the control virus at 24 hpi, indicating no enhancement of viral replication by rCq-GABARAP treatment at this infection stage." (PMID 27385304, 2016). "Surprisingly, the Cq-GABARAP-mediated enhancement of viral entry did not facilitate WSSV replication but significantly suppressed viral replication at 6 hpi, which is an early stage of infection." (PMID 27385304, 2016).
Bacterial infections (1 paper, 2021). "Pathway analysis revealed multiple related functions of the new features, such as Viral mRNA Translation (INMT), GABA receptor binding (GABARAP), Bacterial infections in CF airways (TOLLIP), signaling (RALGDS) and others." (PMID 34302024, 2021).
heart disease (1 paper, 2019). "Thus, GABARAP is required for Granule of BU-XIN RUAN-MAI exhibiting its protective effect against heart disease, and it is meaningful for us to investigate the role of GABARAP in Granule of BU-XIN RUAN-MAI against heart disease." (PMID 31949464, 2019). "Firstly, GABARAP was decreased in the heart of ISO-induced rats and in angiotensin II-incubated HUVEC cells, whereas it was upregulated by Granule of BU-XIN RUAN-MAI, implying that GABARAP-mediated autophagy might be involved in Granule of BU-XIN RUAN-MAI alleviating heart disease." (PMID 31949464, 2019).
GABARAP also shares sentences with these, for which no sentence is quoted: viral infection (4 papers); Parkinson’s (2); schizophrenia (2); stiff-person syndrome (2); age (1); amyotrophic lateral sclerosis (1); arteriosclerosis (1); cerebellar ataxia (1); colorectal tumors (1); depressive disorder (1); Diabetes (1); hematological malignancies (1); immunotoxicity (1); Insulin resistance (1); invasive ductal carcinoma (1); liver cancer (1); mantle cell lymphoma (1); nematode infection (1); Neurodevelopmental delay (1); neurological disorders (1); osteoarthritis (1); pancreatic adenocarcinoma (1); rheumatoid arthritis (1); skin tumor (1); small cell lung carcinoma (1); tauopathy (1); thyroid tumor (1).